INPP4B (inositol polyphosphate-4-phosphatase type II B)
Diseases named in the same sentence as INPP4B in open-access papers (continued):
Sharing a sentence is not in itself a finding about the gene and the disease.
tumor (continued). "Expression of both INPP4B and PTEN is frequently lost in thyroid and endometrial cancers, suggesting a co-operative tumour suppressor function for both enzymes." (PMID 28082369, 2017). "The resulting facets give us information that shows that three genes HRSP12, INPP4B and ZNF827 contain integrations in both the normal and the tumor samples." (PMID 28969593, 2017). "Another lipid phosphatase, inositol polyphosphate 4-phosphatase type II (INPP4B), has recently been shown to have potential tumor suppressor activity." (PMID 27484095, 2016). "Inositol polyphosphate 4-phosphatase type II (INPP4B) negatively regulates PI3K/Akt signalling and has a tumour suppressive role in some types of cancers." (PMID 26573229, 2015). "The role of inositol polyphosphate 4-phosphatase type II (INPP4B), another tumor suppressor, is increasingly recognised." (PMID 26779371, 2015). "Additionally, dynamic IPA site usage was observed in well-known tumor suppressor genes, including TSC1, HSD17B2, CD58, RUNX1 and INPP4B." (PMID 41218079, 2025). "Alternatively, in this context, the inactivation of tumor suppressors such as phosphatase and tensin homolog deleted on chromosome 10 (PTEN) or depletion of the inositol polyphosphate 4-phosphatase type II (INPP4B) also leads to hyperactivated PI3K/AKT signaling." (PMID 41408399, 2025). "An integrative analysis of breast cancer patient chores using data from The Cancer Genome Atlas (TCGA) and the Clinical Proteomic Tumor Analysis Consortium (CPTAC) identified several genes, including GRB7, INPP4B, and MLPH, that are specifically overexpressed in the HER2-positive subtype." (PMID 41008874, 2025). "Inoculated etoposide resistant, INPP4B overexpressing Y79 cells did not generate significantly smaller tumors, but the tumor formation capacity was significantly decreased compared to chemosensitive control cells." (PMID 36993823, 2023). "Consistent with the INPP4B tumor suppressor function, the tumorigenic markers MAPK, SRC, and SNAI2 were elevated, and the tumor suppressor proteins RB1, BRCA1, and CHEK2 were decreased in the cells treated with siRNA targeting INPP4B." (PMID 38001678, 2023). "Notably, INPP4B is a known inhibitor of the PI3K/AKT mediated growth pathway; knockdown experiments clearly showed the tumor suppressive role of INPP4B." (PMID 35327452, 2022). "There are currently no described INPP4B inhibitors available, and given its capacity to function as both a tumor suppressor and oncogene, therapeutically targeting this lipid phosphatase presents a significant clinical challenge." (PMID 36612130, 2022). "Inpp4b‐silenced 4C11+ cells (siInpp4b) did not result in any significant differences in tumor size and weight when compared to control cells." (PMID 35075772, 2022). "Collectively, our results indicate that the expression level of INPP4B may be related to tumour size, histopathological differentiation and TNM tumour stage." (PMID 34729121, 2021). "INPP4B protein expression in tumours is still controversial and has not been studied in GBC tissues." (PMID 33879096, 2021). "However, in the large tumour size (≥6 cm) group, low-undifferentiated group and TNM advanced stage group (III-IV), GC patients with INPP4B+ seemed to have a shorter OS than patients with INPP4B- (respectively)." (PMID 34729121, 2021). "Since PTEN and INPP4B can restrain oncogenic activation of Akt, it is not surprising that loss of PTEN or INPP4B expression or function promotes tumor growth in murine cancer models through enhanced Akt isoform-specific signaling." (PMID 29562639, 2018). "Direct evidence has been presented for a context-dependent role for INPP4B as a tumor suppressor, with deletion of Inpp4b driving tumor formation in mouse thyroid only in the absence of one allele of Pten." (PMID 29056325, 2017). "By Western blotting, we confirmed the increase of p-AKT (Thr308) in the NPC tumor lines (C666-1, C15, C17 and X99186) in which the expression of INPP4B is reduced or absent." (PMID 25126743, 2014).
tumor (continued). "Westbrook and colleagues identified INPP4B as a tumorigenesis-restraining gene in a nonbiased RNA interference-based screen for genes with functional relevance to tumor initiation and development that suppress transformation of human mammary epithelial cells." (PMID 22121480, 2012). "Further evidence of INPP4B as a tumor suppressor gene comes from a nonbiased RNAi-based genetic screen." (PMID 22121480, 2012). "Two years later INPP4B was identified as a potential tumor suppressor in a non-biased screen for transcripts that inhibit transformation of human mammary epithelial cells (HMEC)." (PMID 21487159, 2011). "Whether INPP4B functions solely in a tumour suppressing or tumour promoting manner, or both in non-transformed cells is currently not clear." (PMID 31695845, 2019). "Furthermore, we found that gene expression of INPP4B, CDK1, and ERBB2 was statistically significantly connected with patient survival in the same manner as the commonly used reference genes ESR1 (for ER status) and MKI67 (for tumor grade or proliferation)." (PMID 31315058, 2019).
cancer (61 papers, 2011 to 2026). A tumor composed of atypical neoplastic, often pleomorphic cells that invade other tissues. "Nevertheless, mechanisms underlying the context-dependent cancer functions of INPP4B remain to be elucidated." (PMID 31695845, 2019). "In these studies, INPP4B loss resulted in elevated Akt activation, increased cell survival and a more aggressive growth phenotypes associated with poor outcomes for cancer patients." (PMID 31695845, 2019). "This seemingly paradoxical association of INPP4B expression with cancer suggests that the role of INPP4B in cancer is cell type- or context-dependent." (PMID 29415082, 2018). "Pan-cancer analysis with CoxPH SubID revealed that INPP4B expression status was significantly associated with patient survival in 13 cancers (P<0.05, FDRA.C<0.05)." (PMID 29415082, 2018). "Low levels of INPP4B expression (INPP4Blow) in 8/13 cancers were associated with favourable prognosis cancers, whereas 5/13 cancers were associated with poor prognosis." (PMID 29415082, 2018). "The review by Woolley et al23 summarized the mechanism underlying the complexity in function of INPP4B in cancer." (PMID 29516642, 2018). "Previous studies demonstrated the prognostic significance of INPP4B protein loss or overexpression across some different cancer types." (PMID 29415082, 2018). "The mutation or low expression of INPP4B has been closely related to the poor prognosis of these cancers." (PMID 25962159, 2015). "In addition, INPP4B protein expression is reduced in several cancers, and its low expression is associated with a poor prognosis 11-14." (PMID 34729121, 2021). "Low expression of INPP4B in several cancer types is associated with poor clinical outcomes." (PMID 33879096, 2021). "Therefore, our findings would offer targeting INPP4B deficiency or defects as a promising therapeutic strategy for personalized cancer treatment in the clinic." (PMID 32341333, 2020). "Our finding that destabilization of Rad50 induced by loss of INPP4B may reveal the Achilles’ heel of certain cancers." (PMID 32341333, 2020). "Notably, the loss of INPP4B correlates with poor prognosis in human cancer, including cancers of the male reproductive system." (PMID 32413098, 2020). "Furthermore, INPP4B has been implicated in regulation of DNA damage sensitivity in a number of cancer cell lines including breast cancer cell line MDA-MB-231, leukemia cell line KG-1 and ovarian cancer cell line Ovca42916–18." (PMID 32341333, 2020). "Reduced expression of PI3K pathway enzymes such as PTEN, PIPP and INPP4B is frequently observed in human cancers, which may be due to loss of chromosomal regions, mRNA or protein expression." (PMID 28082369, 2017). "Although the degree of INPP4B loss that is needed for cancer cells to down-modulate ATR and BRCA1 levels and to acquire sensitivity towards PARP inhibitors still needs to be determined, we found that INPP4B loss greater than 50% in MEFs resulted in reduced levels of BRCA1, ATM and ATR proteins." (PMID 25868852, 2015). "However, the MAF of the INPP4B disease-associating SNP (rs17016021) is rather rare, i.e. 0.026, suggesting that dysfunction of the pathway represented by INPP4B is less likely to occur whose mutation functions as a pivotal switch toward enhanced cancer cell proliferation potential." (PMID 31872854, 2020). "It has recently been shown that Inpp4b directs ILC1 homing to cancer tissues using NCRiCre/Inpp4bfl/fl mice." (PMID 38969652, 2024). "In these cancer cell lines INPP4B signaling, however, increased proliferation and anchorage-independent growth." (PMID 36993823, 2023). "Recently, increasing evidence showed that INPP4B is a negative regulator of the PI3K/Akt signaling pathway in many cancers." (PMID 35070988, 2021). "In response to chemotherapy, KU‐55933 inhibits ATM‐mediated repair signals in the presence of inositol polyphosphate‐4‐phosphatase type II (INPP4B), which has contradictory roles in cancer progression." (PMID 34977872, 2021).
cancer (continued). "The advances achieved recently shed new light on the pivotal role of inositol polyphosphate 4-phosphatase type II (INPP4B)-mediated signaling in the regulation of cancer survival, motility, and invasiveness." (PMID 35070988, 2021). "Herein, we describe the development and application of SubID and use the expression of Inositol Polyphosphate 4-Phosphatase type II (INPP4B) as a representative gene expression-based biomarker for predicting patient survival across cancers." (PMID 29415082, 2018). "CoxPH SubID application to our pan-cancer study identified 13 cancers where INPP4B expression status was prognostically significant." (PMID 29415082, 2018). "Inositol polyphosphate 4-phosphatase type II (INPP4B), a new factor in the phosphoinositide-3 kinase (PI3K) pathway-associated cancers, has been recently found a clinically relevant role in AML." (PMID 29343273, 2018). "Our results shed new light on the complex mechanism of the paradoxical function of INPP4B in cancer." (PMID 29516642, 2018). "Nevertheless, more mechanistic studies will solidify our understanding of this contextual role for INPP4B in cancer." (PMID 29415082, 2018). "The INPP4B protein is a phosphoinositide phosphatase and acts as an important regulator in PI3K pathway-associated cancer." (PMID 29343273, 2018). "Consistent with literature, this systematic analysis reveals that the relationship between INPP4B and cancer survival is context dependent." (PMID 29415082, 2018). "It seems that the role of INPP4B in the pathogenesis of cancer is highly cell type- and context-dependent." (PMID 26573229, 2015). "Our work is the first report to show pathophysiological characterization of how ERα interplays with INPP4B to inhibit bladder malignant transformation and cancer growth in vivo as well as in vitro." (PMID 25277204, 2014). "Thirty-nine out of 52 (75%) low-grade tumors were INPP4B positive, whereas 41 out of 77 (53%) high grade carcinomas were INPP4B-positive (P=0.016)." (PMID 25277204, 2014). "We will review its structure and function, crosstalk with androgen receptor signaling, and regulation of INPP4B expression, as well as existing data about its role in cancer." (PMID 21487159, 2011). "Notably, a 2022 study revealed that ELOVL2 is significantly upregulated in PCa compared to normal prostate tissue and regulates cancer cell behavior through INPP4B signaling, further underscoring its importance in PCa progression." (PMID 40552308, 2025). "MCM3 and INPP4B has been reported before to be related to cancer, while other three might be potential candidates for further study." (PMID 35842613, 2022). "More recently, an increasing number of studies have shown that INPP4B may be upregulated frequently and may play an oncogenic role in several types of cancers 16-18." (PMID 34729121, 2021). "Paradoxically, INPP4B is also a reported oncogene in other cancers." (PMID 34035258, 2021). "The PI3K/Akt signaling pathway and the mammalian target of rapamycin (mTOR) signaling pathways are two pathways crucial to many aspects of cell growth and survival in cancers, and a recent study has revealed that INPP4B suppressed the PI3K/Akt/mTOR signaling in cervical cancer cells." (PMID 35070988, 2021). "Evidence accumulated from basic and clinical studies suggests that INPP4B may play a very controversial role in cancer progression." (PMID 34729121, 2021). "However, due to the paradoxical roles of INPP4B in the prognosis of GC patients and other cancers, further biological experiments and mechanistic studies of INPP4B in GC are necessary." (PMID 34729121, 2021). "In fact, our finding that INPP4B knockout A549 cells are sensitive to DNA repair inhibitor olaparib further supports the scenario of defected DNA repair could be exploited for cancer therapy." (PMID 32341333, 2020).
cancer (continued). "In conclusion, our study has revealed an unanticipated role of tumor suppressor INPP4B in maintenance of genome integrity by facilitating Rad50 mediated DNA double-strand break repair, provided a new therapeutic strategy for INPP4B-based therapy for cancer treatment." (PMID 32341333, 2020). "Conversely, emerging evidence suggests that INPP4B overexpression may also promote tumourigenesis and cancer progression." (PMID 31695845, 2019). "A growing body of evidence links altered levels of INPP4B expression to the progression of cancer." (PMID 31695845, 2019). "Altogether, these findings point to a putative contextual role for INPP4B in cancer." (PMID 31695845, 2019). "Cancers with prognostically significant INPP4B expression status." (PMID 29415082, 2018). "Despite emerging studies, much remains unclear about the consequences of differential INPP4B expression in cancer including: how expression is regulated and the relationship between INPP4B expression levels and patient outcome." (PMID 29415082, 2018). "Despite its function being poorly understood, emerging data suggested that INPP4B may have a context dependent role in cancer." (PMID 29415082, 2018). "Next, we used CoxPH SubID to conduct a pan-cancer analysis of INPP4B’s prognostic significance." (PMID 29415082, 2018). "To date, little evidence of INPP4B inactivating mutations or deletions in human cancers has been provided." (PMID 29952716, 2018). "Despite emerging evidence demonstrating the prognostic value of INPP4B expression levels in some cancers, the prognostic value of INPP4B gene expression across many cancers remains unknown." (PMID 29415082, 2018). "A more comprehensive characterization of INPP4B’s prognostic value across cancers could provide a starting point for studies examining a mechanism responsible for INPP4B’s observed context-dependent nature." (PMID 29415082, 2018). "Thus, in this study, we systematically examined the prognostic significance of INPP4B expression status across all TCGA datasets from 25 different cancer types." (PMID 29415082, 2018). "In addition to uncovering EVI1 as transcription factor regulating INPP4B expression, SubID was also used to examine the prognostic significance of INPP4B expression status across cancers." (PMID 29415082, 2018). "Thus, the pan-cancer analysis once again reveals the opposing relationship between INPP4B expression and patient outcome." (PMID 29415082, 2018). "Aberrations of this pathway are extensively found in many human cancers in a variety of forms, including mutation or amplification of PIK3CA and loss of phosphatase and tensin homolog (PTEN) and inositol polyphosphate 4-phosphatase-II (INPP4B)." (PMID 25542038, 2014). "Moreover, INPP4B deficiency affects BRCA1, ATM and ATR protein stability, which may lead to the defect of DNA repair machinery and, ultimately, uncontrolled cancer growth." (PMID 31872854, 2020). "Together these findings suggest that INPP4B may be a context dependent cancer gene." (PMID 31695845, 2019). "INPP4B may have more diverse molecular functions beyond its role as a lipid and protein phosphatase, and examination of potential protein–protein interactions may further elucidate its complex and dynamic role in cancer signalling." (PMID 28082369, 2017). "In turn, INPP4B inhibits AKT phosphorylation, which inhibits malignant cell migration and invasiveness, and exerts a suppressive role on cancer progression." (PMID 36147923, 2022). "Inositol polyphosphate 4-phosphatase type II (INPP4B) is a negative regulator of the PI3K-Akt signalling pathway and plays a contradictory role in different types of cancers." (PMID 33879096, 2021). "We will review the structures and functions of PTEN, SHIP, INPP4B, and PP2A phosphatases in suppressing cancer progression and their deregulation in cancer and highlight recent advances in our understanding of the PI3K/Akt signaling axis." (PMID 22121480, 2012).
cancer (continued). "SHIP1/2, PP2A, INPP4B, and PTEN are commonly viewed as opposing the activity of the PI3K/Akt signaling axis, which promotes survival of cancer cells and tumors." (PMID 22121480, 2012). "Similar to various mouse models of cancer altering PTEN or Akt activity, valuable data will be obtained by modulating INPP4B expression in the mouse." (PMID 21487159, 2011). "Thus, although its function in different human cancers remains controversial, INPP4B and the mediated PI3K/AKT downstream signaling pathway seem to play an important role in tumorigenesis and cancer progression." (PMID 36993823, 2023). "In different cancers, INPP4B may affect PI3K/AKT/SGK signal output dissimilarly, which contributes to various biological behaviours in those cancer cells." (PMID 29516642, 2018). "As for PTEN, no treatment strategies specifically targeting INPP4B function are currently available, and thus PI3K or its distal effectors might also be targeted in cancers where INPP4B function is altered." (PMID 33672717, 2021).
infection (4 papers, 2015 to 2021). The state of being infected such as from the introduction of a foreign agent such as serum, vaccine, antigenic substance or organism. "GBC-SD and SGC996 control cells and cells with stable INPP4B overexpression and knockdown were established by infection with different lentiviruses." (PMID 33879096, 2021). "To verify our hypothesis, we established AGS and BGC-823 cells stably overexpressing, silenced and negative control INPP4B by infection with different lentiviruses." (PMID 34729121, 2021).
neurological disease (1 paper, 2022). "Our data demonstrates that disruption of INPP4B/PIKfyve‐dependent lysosome reformation leads to protein aggregate accumulation and proteotoxicity, processes that are associated with neurological disease." (PMID 35968799, 2022).
INPP4B also shares sentences with these, for which no sentence is quoted: metastatic melanoma (3 papers); ductal breast carcinomas (2); autoimmune disorders (1); bovine tuberculosis (1); brain glioma (1); colorectal tumours (1); cryptorchidism (1); diffuse large B-cell lymphoma (1); endometrial cancer (1); invasive breast carcinoma (1); lobular carcinoma (1); lymphoma (1); malaria (1); nasopharyngeal carcinoma (1); obstructive jaundice (1); pancreatic (1); prostate (1); prostate adenocarcinoma (1); rectal tumors (1); renal cell carcinoma (1); rheumatoid arthritis (1); squamous cell carcinoma of the lung (1); steatosis (1); T-cell lymphoma (1); teratoma (1).